IL6 (interleukin 6)
Diseases named in the same sentence as IL6 in open-access papers (continued):
Sharing a sentence is not in itself a finding about the gene and the disease.
COVID-19 (continued). "Although there is an interplay between IL-1, IL-6 and multiple other cytokines, IL-6 inhibition appears to be superior to IL-1 inhibition in COVID-19 and remains the main focus of therapy." (PMID 36987476, 2023). "Accordingly, several interleukins (e.g., IL-3, IL-6 or IL-10) have been identified as predictors of adverse events and higher mortality in COVID-19." (PMID 36769623, 2023). "This multifaceted action contributes to the reduction in IL-6 levels, making pirfenidone a potential treatment option for COVID-19 by dampening the inflammatory response and addressing fibrotic triggers." (PMID 38248752, 2023). "Various cytokines, particularly interleukin-1b, interleukin-6 (IL-6), and tumor necrosis factor-α, were elevated in mild and severe COVID-19 patients." (PMID 37234160, 2023). "From the analysis, ACE inhibitors came out as highly potent drug candidates against COVID-19 along with immunomodulatory monoclonal antibodies (anti-IL6, anti-IL12, etc.)." (PMID 37109050, 2023). "In severe COVID-19 patients, IL-6 levels positively correlated with the levels of Adiponectin, Visfatin, Resistin and negatively correlated with plasma leptin levels." (PMID 36509969, 2023). "A recent meta-analysis also revealed that IL-6 is a master regulator of COVID-19 severity biomarkers." (PMID 37888066, 2023). "Based on exist evidence, cytokines are central to the pathophysiology of COVID-19; while some of them are beneficial, others appear detrimental such as interleukin-6 particularly in the context of the cytokine storm." (PMID 37161412, 2023). "Elevated levels of myoglobin, troponin, creatine kinase-MB, plasma interleukin-6, lactate dehydrogenase (LDH), and N-terminal pro-b-type natriuretic peptide (NT-proBNP) have been found in COVID-19-associated myocardial injuries." (PMID 37009373, 2023). "There were distinctive two groups of critical COVID-19 according to serum IL-6 levels having different degrees of cytokinemia and T-cell responses." (PMID 37081872, 2023). "Several studies showed a significant increase in inflammatory cytokines, such as IL-3, IL-6 and IL-10, among patients with a severe or lethal disease course of COVID-19." (PMID 36769623, 2023). "Significant differences were registered between the form of COVID-19 depending on the vaccination status, between LDH concentrations depending on the virus variant, and in IL-6, CRP, and ferritin concentrations and vaccination status depending on the gender." (PMID 37239895, 2023). "Previous studies have reported the impact of hyperglycemia on severe outcomes of COVID-19 in the acute phase, as well the reduced efficiency of tocilizumab therapy, an inhibitor of IL-6 cytokine signaling." (PMID 35898449, 2022). "Univariate logistic regression analyses of IL-6 signalling biomarkers as predictors of COVID-19 mortality." (PMID 35634332, 2022). "Cytokine storm, characterized by massive release of IL-6 and other cytokines, frequently developed in severe COVID-19, leading to a marked elevation of CRP." (PMID 36035233, 2022). "In conclusion, we showed that patients with NAFLD have a different immune response to severe COVID-19, with IL-6, IL-8, IL-10, and CXCL10 as a possible culprits of an uncontrolled inflammation associated with disease severity in this group of patients." (PMID 35743825, 2022). "The patients of the second wave showed lower levels of iNOS, IL-6, and IL-10, as compared to the corresponding subgroup of the first wave, suggesting a less severe outcome of COVID-19 in these patients." (PMID 35336941, 2022). "Next, the measured plasma cytokine IL-6 was utilised as a proxy for COVID-19 severity, reflecting the extent of the inflammatory response." (PMID 35888742, 2022). "Although dramatic elevation of IL-10 and IL-6 with inflammatory markers such as C-reactive protein have been reported in severe or critical COVID-19 cases." (PMID 36094915, 2022).
COVID-19 (continued). "Outbreaks of COVID-19 are accompanied by immunocompromised through hyperexpression of both proinflammatory (IL-1, IL-2, IL-6, and TNF-α) and anti-inflammatory (IL-4, IL-10, and IL-17) cytokines, and vice versa with IFN-γ." (PMID 36045713, 2022). "Our present study was designed to investigate the ability of the different components in serum of IL-6 signalling including IL-6, sIL-6R, and sgp130 to discriminate severity and to predict disease course and outcome in COVID-19 patients." (PMID 35634332, 2022). "Altogether, the data indicate that IL-6 signalling markers as well as the indicators of IL-6 trans-signalling are efficient predictors of COVID-19 disease progression in terms of severity and mortality." (PMID 35634332, 2022). "Various studies have demonstrated the correlation of hypercytokinemia with the breadth of lung injury, multiorgan failure, ICU admission and poor survival rates (especially with IL-6 levels) in COVID-19 patients." (PMID 35874775, 2022). "Immunomodulatory drugs that can currently be used in COVID-19 are those aimed at inhibiting IL-6 and IL-1, thus preventing the effects of activation of the pro-inflammatory cascade." (PMID 36579506, 2022). "Analysis of the AUROC curve was used to assess the efficacy of IL-6 signalling-related variables as potential discriminators of COVID-19 severity (focused on severe patients who survived the disease)." (PMID 35634332, 2022). "A recent study demonstrated a negative association between the total count of T cells, CD4+, and CD8+, and the TNF-α and IL-6 levels in ICU patients due to the COVID-19." (PMID 35456120, 2022). "Cytokine storms begin with strong activation of cytokine-secreting cells, and COVID-19 cytokine storms are characterized by high expression of IL-6 and TNF-α." (PMID 36091053, 2022). "In our knowledge, our study is first among all to correlate IL-6 with other inflammatory markers in COVID-19 and show its role in treatment and prognosis of the disease." (PMID 36366295, 2022). "Following rapid conduct of clinical studies to treat COVID-19, accepted cytokine-suppressing treatments that reportedly lower mortality include drugs that block IL-6 biological activity and the immunosuppressive corticosteroid dexamethasone." (PMID 35814227, 2022). "AF incidence in our cohort is similar to that reported in other studies; however, the present study highlights that new-onset AF is related to IL-6 serum levels in COVID-19 patients even when stratified according to ARDS status." (PMID 35454369, 2022). "Severe COVID-19 cases developed more bilateral ground-glass pneumonia and had higher serum ferritin and IL-6 levels." (PMID 35962159, 2022). "Abnormally high levels of IL-6 are an indicator of poor outcome in COVID-19 patients with pneumonia and ARDS." (PMID 35342348, 2022). "Collectively, all the cytokines and chemokines contribute to COVID-19 immunopathology, yet IL-6, IFN, IL-17, TGF-β, TNF-α, and CXCL10 are believed to have major roles in the lung pathogenesis post-SARS-CoV-2 infection." (PMID 35062368, 2022). "We conducted a longitudinal study to investigate the role of IL-6 in diagnosis, treatment, and prognosis of COVID-19-related cytokine storm." (PMID 36366295, 2022). "Supporting this, patients with severe COVID-19 had markedly higher levels of IL-6 and TNFα pro-inflammatory cytokines compared to patients with mild-to-moderate disease." (PMID 35468973, 2022). "Tocilizumab is able to block the IL-6 soluble and membrane receptor, approved for severe forms of COVID-19, characterized by the overproduction of proinflammatory cytokines." (PMID 36359334, 2022). "As with other hyperinflammatory disorders, inflammatory mediators such as interleukin-1 and interleukin-6 have been therapeutic targets in COVID-19 clinical trials with varying success." (PMID 35698050, 2022). "In particular, the level of IL-6 rises during COVID-19 illness, falls as patients recover, and is correlated with the severity of the disease." (PMID 35928369, 2022).
COVID-19 (continued). "STAT3 is seen as one of the key elements of cytokine storm pathogenesis and other complications in COVID-19 that target IL-6." (PMID 35327350, 2022). "One meta-analysis showed reported benefit for IL-6 inhibitor therapy restricted to the anti-IL-6 receptor antibody preparation tocilizumab (WHO Rapid Evidence Appraisal for COVID-19 Therapies (REACT) Working Group, 2021)." (PMID 35814227, 2022). "Clinical guidelines from the National Institute of Health in the United States now advice against the use of hydroxychloroquine, chloroquine, Azithromycin, Tocilizumab (Actemra) and other IL-6 inhibitors, and kinase inhibitors) for treating COVID-19." (PMID 35969603, 2022). "The results of our meta-analysis showed that Asian, European, and African patients with severe COVID-19 had elevated circulating IL-6 levels and the circulating IL-6 levels of European and African was higher than the Asian patients." (PMID 35237162, 2022). "Serum IL-6 elevation is observed in severe cases of COVID-19, and excessive IL-6 released from macrophages triggers a cytokine storm and leads to immune exhaustion." (PMID 35252273, 2022). "An additional proposed pattern of immune dysregulation in severe COVID-19 is characterized by excessive release of IL6, sustained inflammation and profound lymphopenia." (PMID 36365007, 2022). "Recent evidence proposed that the severity of the coronavirus disease 2019 (COVID-19) in patients is a consequence of cytokine storm, characterized by increased IL-1β, IL-6, IL-18, TNF-α, and IFN-γ." (PMID 36111104, 2022). "In fact, significantly lower levels of CD8+ T cells and increased levels of IL-6 have been shown to be reliable indicators of developing severe COVID-19 while the T cells that remain appear functionally exhausted." (PMID 34050887, 2022). "Our study showed a significant decrease in IL-6 production by PBMCs and neutrophils, as well as a significant increase in serum levels in intensive care patients with COVID-19, compared with healthy controls." (PMID 36363785, 2022). "By using the AFM as nanosensor, our cell culture data suggests that in COVID-19, the endothelial surface is attacked and the eGC deteriorates in relation to disease severity (mild vs severe course) and in correlation to the IL-6 level." (PMID 35867189, 2022). "Studies showed a decrease in miR-146a-5p expression and an increase in IL-6 levels in patients with COVID-19 compared to that in healthy people." (PMID 36204652, 2022). "This syndrome is characterized by release of interleukin 6 correlated with COVID-19 severity and mortality." (PMID 35200527, 2022). "Several studies have found significantly high levels of inflammatory cytokines such as TNF-α and IL-6 in COVID-19 patients." (PMID 36092161, 2022). "Systemic inflammatory cytokine/chemokine response including TNFα, IL-6, MCP-1, IP-10, and MIP-1α has been associated with more severe disease in human studies of COVID-19." (PMID 35789343, 2022). "Analysis of postmortem tissue from people who died due to influenza, bacteria pneumonia, ARDS, and COVID-19 has recently shown that activated (IL-1β– and IL-6–producing) monocytes and macrophages are significantly more abundant in the COVID-19 lung." (PMID 34710339, 2022). "Many documents revealed that those who died because of COVID-19 had higher serum levels of interleukin IL-6 compared to survivors." (PMID 36111104, 2022). "TNF-α and IL-6 production upon different stimuli were similar between healthy individuals and convalescent COVID-19 patients." (PMID 35464396, 2022). "Meanwhile, the concentration of IL-6 in patients with COVID-19 was significantly higher than that in the general population." (PMID 35795627, 2022). "Some studies have reported that IL-6 is the most important single cytokine in the cytokine storm seen in patients with COVID-19." (PMID 35907817, 2022).
COVID-19 (continued). "In conclusion, the nomogram (including age, dyspnea, lymphocyte count, CRP and IL-6) objectively and accurately prewarns the severe disease occurrence out of common type COVID-19 patients." (PMID 35037900, 2022). "In a prospective cohort study comparing the prognostic role of inflammatory markers in COVID-19 and other respiratory infections, IL-6 and CRP are reported as the strongest predictors for ICU admission or death, at 30 days." (PMID 36142336, 2022). "Higher concentrations of serological TNF-α, IL-6, MIP1b and IL-4 were observed within the P-COVID-19+ group, while cytokines and chemokines secreted by peripheral leucocytes in response to LPS, IL-6 or PMA-ionomicin were similar among the groups." (PMID 35901034, 2022). "This study also found that IP-10 and IL-6 were significantly higher in severe cases of COVID-19 compared to mild cases." (PMID 35273264, 2022). "IL-6 is directly associated with inflammatory lung conditions and targeting IL-6 pathways can effectively treat a variety of inflammatory conditions and decrease mortality in severe COVID-19 cases." (PMID 35617421, 2022). "Increased CXCL2, CXCL8, IL-6, and IL-1β are consistent with neutrophilia that is often seen in COVID-19 patients, particularly in those who are severely ill." (PMID 35757770, 2022). "Patients with low FT3 and older age showed a worse prognosis and higher levels of the COVID-19 severity markers IL-6 and IL-10 than patients with high FT3." (PMID 36440226, 2022). "In contrast, one meta-review found that IL-6 levels, while elevated, were at least one order of magnitude lower in COVID-19 patients than in those with non-COVID-19-related ARDS and sepsis, suggesting a different mechanism of immune dysregulation." (PMID 35336888, 2022). "In the analysis of the antiviral cytokines, only two cytokines were significantly higher in the low-FT3 group, IL-6 (p=0.016) and IL-10 (p=0.015), both defined as markers of COVID-19 severity." (PMID 36440226, 2022). "IL-6 was used to develop tocilizumab, a drug that clinically treats arthritis and alleviates the symptoms of COVID-19 by targeting interleukin-6 receptors." (PMID 35707470, 2022). "The purpose of this study was therefore to analyze the correlations between the olfactory scores determined by psychophysical tests and the serum levels of IL-6 in patients affected by COVID-19 and admitted to the University Hospital of Sassari." (PMID 33983525, 2022). "An aberrant immune-response characterized by uncontrolled hyperinflammation has been described in severe COVID-19 patients, and elevated blood levels of interleukin 6 (IL-6) have been related to a fatal outcome." (PMID 35081151, 2022). "The data demonstrated that PDGF, IFN-γ and IL-6 exhibited elevated global accuracy (AUC>0.9) as reliable soluble mediators to sort COVID-19 patients from HC." (PMID 36451835, 2022). "Overproduction of IL-6 is more significant compared with other cytokines in the severe form of COVID-19." (PMID 35782361, 2022). "Another study recorded that the mean IL-6 levels were 2.9 times higher in complicated COVID-19 patients compared with uncomplicated COVID-19 patients." (PMID 35215138, 2022). "Treatment for COVID-19 included corticotherapy in 78% (431/553), anti-IL-6 tocilizumab in 6% (34/553), anti-IL-1-anakinra in 16% (89/553), and antivirals, including remdesivir in 22.4% (124/553), favipiravir in 15.6% (86/553) and umifenovir in 0.5% (3/553)." (PMID 35743662, 2022). "A SNP that disrupts the conserved CTCF-binding site has been shown to attenuate IL-6 induction in COVID-19, thereby providing protection from severe outcomes." (PMID 36398441, 2022). "The elevation of IL-6 and TNF-α was shown to be associated with the severity of COVID-19 due to the cytokine storms, and remarkable elevation of plasma LGALS3BP was also observed in COVID-19 ICU patients." (PMID 35958562, 2022).
COVID-19 (continued). "IL-6 is a biomarker for the development of severe COVID-19, and it has been exploited as a potential cytokine target for therapy." (PMID 36233840, 2022). "Of note, we observed distinct top correlating miRNA for each severity group for all tested CC, including for example IL6 and CCL20, two cytokines strongly associated with COVID-19 severity in our data." (PMID 34957382, 2022). "Our findings also align with the results of a study conducted on 41 COVID-19 confirmed cases in China, which found that IL-6, IL-7, TNF, and IL-10 were upregulated in the plasma of the study subjects." (PMID 36239108, 2022). "Patients with COVID-19 appear to have delayed IFN responses that results in upregulation of the cytokines IL-6, IL-7 and TNF-α." (PMID 35601440, 2022). "Further studies are needed to support the use of IL-6 as an early molecular target for COVID-19 patients to reduce their high rate of mortality." (PMID 35454369, 2022). "Serum proteomics studies in patients with COVID-19 have found that abnormal increases in IL-6 correlate with increases in the coagulation and complement cascade components." (PMID 35784318, 2022). "The important roles of IL-6 in the pathogenesis of cytokine storm have already been elucidated, but recently, its functions in the pathogenesis of COVID-19 have received more attention." (PMID 35047633, 2022). "Among COVID-19 patients, the most common disorders of cytokines and chemokines are increased levels of IL-1β, IL-2, IL-6, interleukin-7 (IL-7), IL-10, TNF-α, CRP, chemokine ligand 2 (CCL2), as well as an increase or decrease in the concentration of IFN-γ." (PMID 36294388, 2022). "COX regression analyses of IL-6 signalling components as predictors of COVID-19 mortality based on proposed scores." (PMID 35634332, 2022). "In controlled clinical trials throughout the world, IL-6 and IL-6R antagonists are being evaluated for the treatment of COVID-19 patients with severe respiratory difficulties." (PMID 36506506, 2022). "A meta-analysis study including 37 studies showed that mean IL-6 concentration was 55.3 and 37.3 pg/ml in patients with critical and severe COVID-19, respectively." (PMID 35242747, 2022). "Most patients under IL-6 inhibition show clinical improvement of symptoms such as hypoxia and changes in computed tomography (CT) opacity immediately after treatment, suggesting that this could be an efficient therapy for the treatment of COVID-19 with decreased 28-day all-cause mortality." (PMID 35720401, 2022). "The higher IL-6 the levels in COVID-19 patients, the lower the number of NK lymphocyte subsets, including NKT cells, NK cells, immature NK cells, and mature NK cells." (PMID 36403042, 2022). "qRT-PCR confirmed the expected induction of immune-response markers CXCL2 and IL-6 in COVID-19 patients from this cohort." (PMID 35998224, 2022). "By stratifying patients in Long-COVID-19 and No-COVID-19, SDNN was lower in Long-COVID-19, while LF/HF ratio, D-dimer, NT-Pro-BNP, and IL-6 were significantly higher in Long-COVID-19 patients." (PMID 35632776, 2022). "A recent study of in-hospital COVID-19 patients from China reported that the COVID-19 severity was correlated with increased blood levels of IL-6 and lactate dehydrogenase (LDH)." (PMID 36140191, 2022). "Given the potential impact on the immune system, COVID-19 treatment with immunomodulatory drugs, such as IL-6 inhibitors, should be reserved for selected patients according to existing guidelines." (PMID 35806905, 2022). "Many studies have highlighted an increased production of some cytokines, such as IL-6, in patients affected by COVID-19." (PMID 36498859, 2022). "Further, we also investigate the relationship between the IL-6 and COVID-19 patients with the different levels of disease severity in 584 individuals measured with T cells, B cells, NK cells, and 125 individuals measured with lymphocyte subsets, respectively." (PMID 36403042, 2022).